MIF (macrophage migration inhibitory factor)
Diseases named in the same sentence as MIF in open-access papers (continued):
Sharing a sentence is not in itself a finding about the gene and the disease.
cyst (continued). "Therefore, MIF-dependent cyst enlargement may either be driven indirectly via attracted macrophages or in a direct way." (PMID 32885302, 2020). "In addition, MIF can be secreted by tubular cells and may contribute to cyst growth in an autocrine manner." (PMID 32885302, 2020). "In addition, MIF has been shown to be upregulated and promote cyst growth in an ADPKD mouse model." (PMID 32885302, 2020). "Interestingly, HIF-1α and cAMP showed synergistic upregulation of MIF in cyst-forming cells." (PMID 32885302, 2020). "The interaction between MIF and CD74 not only promotes cyst growth but also exacerbates inflammation, contributing to disease progression." (PMID 41431718, 2026). "TNF-α induces MIF expression, which in turn amplifies TNF-α expression in CLECs, forming a positive feedback loop that intensifies cyst progression." (PMID 41431718, 2026). "We have reported that knockout of MIF and targeting MIF with its inhibitor, ISO-1 delayed cyst growth in Pkd1 knockout mouse models." (PMID 38534333, 2024). "The MIF inhibitor ISO-1 attenuates HIF-1α- and cAMP-dependent cyst enlargement and can also be used as a therapeutic target to delay cyst growth in ADPKD." (PMID 37241147, 2023). "Next, we tested the cell permeable MIF-inhibitor 4,5-dihydro-3-(4-hydroxyphenyl)-5-isoxazoleacetic acid methyl ester (ISO-1) in our plMDCK cyst model." (PMID 32885302, 2020). "In contrast, ISO-1 significantly reduced both, expression of MIF and PCNA, suggesting that MIF-dependent cyst enlargement is due to increased cyst cell proliferation." (PMID 32885302, 2020). "MIF is regulated by HIF-1α as well as cAMP, both of which have been shown to promote cyst enlargement in PKD." (PMID 32885302, 2020). "Therefore, we wondered if secreted MIF may increase cyst growth in an autocrine/paracrine way." (PMID 32885302, 2020). "It was recently shown that MIF regulates cyst growth in a murine ADPKD model through several mechanisms and is also accumulated in cyst fluid of human ADPKD kidneys." (PMID 26858715, 2016). "MIF activates CD74 to increase inflammatory cytokines in podocytes and tubular cells and proliferation in glomerular parietal epithelial cells and cyst cells." (PMID 26441987, 2015). "Our results suggested that MIF may be through its receptor CD74 to promote interstitial fibrosis in ADPKD kidneys, and targeting MIF with ISO-1 should ameliorate not only cyst growth but also interstitial fibrosis." (PMID 38534333, 2024). "• MIF-inhibitor ISO-1 reduces HIF-1α- and cAMP-dependent cyst growth." (PMID 32885302, 2020). "In conclusion, HIF-1α and cAMP regulate MIF in primary tubular cells and cyst-lining epithelial cells, and MIF promotes cyst growth in the absence of macrophages." (PMID 32885302, 2020). "Since cyst growth in this model depends on cAMP according to the situation in vivo, we next treated the cells additionally with forskolin (FSK; 10 μM) for 24 h to test for cAMP-dependent effects on MIF expression." (PMID 32885302, 2020). "Therefore, MIF could qualify as a druggable target downstream of HIF-1α and cAMP in order to reduce cyst enlargement and preserve renal function." (PMID 32885302, 2020). "Interestingly, although ICA also results in increased expression of MIF in wildtype kidneys, it does not result in cyst formation." (PMID 32885302, 2020). "Interestingly, CD74 also regulates the transcription of MIF to form a positive feedback loop in that MIF binds with its receptor CD74 to regulate the activity of intracellular signaling pathways and CD74 increases the expression of MIF in ADPKD kidneys during cyst progression." (PMID 38534333, 2024).
systemic sclerosis (17 papers, 2012 to 2025). A chronic disorder, possibly autoimmune, marked by excessive production of collagen which results in hardening and thickening of body tissues. "In particular, the association of the MIF promoter variant rs755622*C allele with systemic sclerosis (SSc) has been demonstrated in a substantial cohort of SSc patients of European descent." (PMID 38790215, 2024). "In contrast, in patients with systemic sclerosis, MIF serum levels were significantly higher than in healthy controls while levels of D-DT are comparable to healthy controls." (PMID 35091838, 2022). "In inflammatory skin diseases, as systemic sclerosis, the fibroblast and mononuclear infiltrating cells produce MIF in skin tissue." (PMID 34533238, 2021). "In patients with PAH secondary to systemic sclerosis, high concentrations of MIF have also been found; therefore, in the future, MIF could be considered as a possible prognostic marker for this pathology." (PMID 36553040, 2022). "In addition to its well characterized role in inflammation and angiogenesis, MIF is upregulated in fibrotic disorders, such as idiopathic pulmonary fibrosis and systemic sclerosis." (PMID 31866994, 2019). "Similarly, dermal fibroblasts from skin wound lesions and systemic sclerosis produced higher amounts of MIF than normal dermal fibroblasts." (PMID 31866994, 2019). "In human, it is reported that patients with PH showed higher MIF levels than patients without these manifestations in systemic sclerosis." (PMID 22363104, 2012).
acute respiratory distress syndrome (16 papers, 2011 to 2025). Progressive and life-threatening pulmonary distress in the absence of an underlying pulmonary condition, usually following major trauma or surgery. "MIF is increased in the blood and bronchoalveolar lavage of patients with acute respiratory distress syndrome and is associated with disease outcome." (PMID 33469074, 2021). "In addition, recent studies observed a strong association between poor outcome and high levels of MIF in patients with severe systemic inflammation, organ failure and/or acute respiratory distress syndrome." (PMID 22506003, 2012). "On the other hand, studies in patients with severe systemic inflammation, organ failure and/or acute respiratory distress syndrome observed a strong association between poor outcome and high levels of MIF, which could be explained by its pro-inflammatory activity." (PMID 22506003, 2012). "It is thought that the ability of MIF to suppress the anti-inflammatory effects of glucocorticoids is central to the inflammatory promoting functions of MIF, for example in diseases such as acute respiratory distress syndrome." (PMID 23522304, 2013). "Clinical studies have shown that MIF has a primary role in endotoxaemia-induced toxic reactions, in sepsis, and acute respiratory distress syndrome (ARDS)." (PMID 21091281, 2011). "MIF also sustains the pulmonary inflammation in the acute respiratory distress syndrome (ARDS)." (PMID 37946732, 2023).
Cerebral ischemia (16 papers, 2011 to 2024). Restriction of arterial blood supply to the brain associated with insufficient oxygenation to support the metabolic requirements of the tissue. "We believe that this study strengthens the evidence that subcortical SBIs undergo hypoxic events similar to acute symptomatic cerebral ischemia by presenting higher MIF levels in patients with subcortical SBIs than in healthy controls." (PMID 39850789, 2024). "Our previous experiments showed that the expression of MIF was the highest at 2 h of cerebral ischemia, so we chose reperfusion at 2 h of cerebral ischemia." (PMID 36797398, 2023). "As MIF was shown to have mitigating effects on oxidative stress, it has also been shown to have protective effects in cerebral ischemia." (PMID 35091838, 2022). "Macrophage migration inhibitory factor (MIF) exerts neuroprotective effects against cerebral ischemia/reperfusion injury by inhibiting neuronal apoptosis and inducing the expression of brain-derived neurotrophic factor (BDNF)." (PMID 33672416, 2021). "Tanshinone IIA showed neuroprotective activity against cerebral ischemia via the inhibition of macrophage migration inhibitory factor." (PMID 34393796, 2021). "In the CNS, as we demonstrated, maintaining MIF expression is important in defending cerebral ischemia by reducing oxidative stress-induced caspase-3 activation in neurons during the acute phase." (PMID 31174614, 2019). "Together, these data suggest a detrimental role for MIF in brain ischemia." (PMID 35091838, 2022). "Tanshinone IIA can reduce the expression of macrophage migration inhibitory factor (MIF) and inflammatory factors (MIF), TNF-α and interleukin (IL)-6 in the brain of rats with cerebral ischemia/reperfusion, thereby alleviating the effects of cerebral ischemia/reperfusion." (PMID 37808475, 2023).
Hyperglycemia (16 papers, 2011 to 2023). An increased concentration of glucose in the blood. "Increased levels of macrophage migration inhibitory factor (MIF) are associated with hyperglycemia and have been linked to the pathogenesis of cardiomyopathy in people with T2DM." (PMID 36871006, 2023). "Some researches have demonstrated that MIF may contribute to hyperglycemia by altering lymphocyte activity." (PMID 38362587, 2023). "The cardioprotective of SPostC could be restored by upregulating the protein expression of HIF-1α and MIF under hyperglycemia." (PMID 33692685, 2020). "Our study indicates that glucose modified and oxidised MIF could be a molecular link between hyperglycaemia and the dysregulation of the innate immune system in AD." (PMID 28230058, 2017). "MIF inhibition normalized hyperglycemia and improved impaired glucose tolerance (ipGTT)." (PMID 26124760, 2015). "Therefore, this study focuses on whether the HIF-1α/MIF/AMPK signaling pathway is a key point in mediating the protective effect of SPostC in hyperglycemia." (PMID 33692685, 2020). "Despite ultimately inducing hyperglycemia and insulinopenia, this model does not bear strong autoimmune features, and as such, it remains highly debatable whether MIF truly contributes to the underlying mechanisms of the autoimmune attack on the β cell." (PMID 29095944, 2017). "Specifically speaking, under the condition of hyperglycaemia, the elevated pro‐inflammatory cytokine, such as TNF‐α and macrophage migration inhibitory factor (MIF), regulates glucose metabolism during systemic inflammation." (PMID 34213839, 2021). "As a ligand of MIF, CD74 protein and mRNA level was significantly up-regulated after STZ-induced hyperglycaemia, as detected by the immunohistochemistry, western blot and RT-PCR analysis." (PMID 25661015, 2015). "It is worth noting that this study found that MIF levels were significantly higher in nondiabetes STEMI patients with stress hyperglycemia than in those with euglycemia, suggesting that MIF is related to stress response." (PMID 30983881, 2019).
lupus nephritis (16 papers, 2015 to 2025). Glomerulonephritis in the context of systemic lupus erythematosus. "Nevertheless, the precise pathogenic mechanisms for MIF's role in lupus nephritis remain to be clarified." (PMID 31608058, 2019). "To date, it is unknown whether kidney injury associated with SLE contributes to elevated serum MIF, and thus future studies examining levels of serum and urine MIF in relation to lupus nephritis are needed." (PMID 26617609, 2015). "Given the longstanding preclinical evidence for a pathogenic role of MIF in glomerular kidney disease, anti-MIF strategies were tested in renal disease, although the sponsor decided to terminate a phase 1 trial of the anti-MIF monoclonal antibody imalumab in lupus nephritis (NCT01541670)." (PMID 26441987, 2015). "In the kidney, interventions to inhibit MIF ameliorated the development of IgAN, crescentic glomerulonephritis, and lupus nephritis in animal studies." (PMID 40458609, 2025). "Circulating levels of MIF are increased in SLE patients and are associated with autoimmune tissue damage, including lupus nephritis and subsequent renal dysfunction." (PMID 35052454, 2022). "Gamez-Nava and colleagues found that levels of MIF were higher in the serum of lupus nephritis patients than levels of MIF in that of HCs and positively correlated with the severity of proteinuria and renal dysfunction." (PMID 34305594, 2021). "To date, the association of serum macrophage migration inhibitory factor (MIF) and serum adipokines with lupus nephritis is controversial." (PMID 33133605, 2020). "In vivo miR-654 treatment decreases MIF and downstream cytokine production and ameliorates murine lupus nephritis." (PMID 31608058, 2019). "We explore specific miRNAs that can regulate MIF expression, and investigate miR-654 for the treatment of experimentally-induced murine lupus nephritis." (PMID 31608058, 2019). "In our previous research, we have reported that miR-152 attenuated the severity of lupus nephritis by downregulation of MIF." (PMID 31608058, 2019). "However, elevated levels of CD74 and MIF positively correlated with worsening inflammation of lupus nephritis from the proinflammatory effects of MIF/CD74 signaling." (PMID 35626874, 2022). "Taken together, these results indicate that miR-654 may play a pivotal role in the progression of lupus nephritis by regulating pathologic MIF overexpression." (PMID 31608058, 2019). "As MIF and inflammatory cytokines play important roles in the pathogenesis of both mouse and human lupus nephritis, we also tested whether miR-654 activated the phosphorylation of ERK and AKT in human THP-1 derived macrophages." (PMID 31608058, 2019). "Additionally, systemic MIF knockout (KO) can also suppress lupus nephritis and anti-GBM CGN." (PMID 38846956, 2024). "Previous studies suggested MIF as a therapeutic target for SLE, as in vivo miRNA inhibition of MIF decreased downstream cytokine production and ameliorated murine lupus nephritis." (PMID 33134397, 2020). "Prior studies have demonstrated the importance of MIF in the pathogenesis of SLE and lupus nephritis." (PMID 31608058, 2019). "Anti-MIF mAb therapy is currently in phase I trials both for solid tumors (NCT01765790) and for lupus nephritis (NCT01541670)." (PMID 26858715, 2016). "Anti-MIF monoclonal antibody therapy is currently in phase I trials both for solid tumors (NCT01765790) and for lupus nephritis (NCT01541670)." (PMID 26617609, 2015). "In one study, a lack of macrophage migration inhibitory factor (MIF) attenuated infiltration of macrophages and alleviated lupus nephritis." (PMID 36311714, 2022).
non-small cell lung carcinoma (16 papers, 2009 to 2025). A group of at least three distinct histological types of lung cancer, including non-small cell squamous cell carcinoma, adenocarcinoma, and large cell carcinoma. "Recent study on non-small cell lung cancers suggested that the co-expression of MIF and its receptor CD74 is associated with greater tumor vascularity and greater of angiogenic CXC chemokines." (PMID 19602232, 2009). "It has been reported that MIF negatively regulates AMPK in human non-small cell lung carcinoma cell lines." (PMID 25617421, 2015). "We have identified two proteins, PTRF/cavin-1 and MIF, which are differentially expressed between normal lung and non-small cell lung cancer." (PMID 22461895, 2012). "In addition, TCGA data showed that high expression of MDK, MIF, and TGFBV1 is associated with poor prognosis in patients with non-small cell lung cancer." (PMID 40948762, 2025). "Their research data showed that this degradation agent can inhibit the proliferation of A549 cells by downregulating the level of MIF in non-small cell lung cancer A549 cells and inhibiting MIF-related signal transduction, proving the potential of PROTAC technology in the treatment of NSCLC." (PMID 36142231, 2022). "The first studies to suggest that MIF may also be involved in governing the activation states of more “M2”-like macrophages came from studies that identified non-small cell lung carcinoma (NSCLC) cell-derived MIF is responsible for increased angiogenic activity of co-cultured human monocytes." (PMID 33324425, 2020). "Since intratumoral expression of MIF was correlated with serum IL-6 in patients with non-small cell lung cancer and IL-6 was shown to be one of the potential MIF-regulated genes in DU145 cells, we speculate that NPRA signaling may regulate IL-6 in PCa cells via MIF." (PMID 21586128, 2011).
pulmonary fibrosis (16 papers, 2015 to 2025). Chronic progressive interstitial lung disorder characterized by the replacement of the lung tissue by connective tissue, leading to progressive dyspnea, respiratory failure, or right heart failure. "SIX1-driven expression of macrophage migration inhibitory factor (MIF) was attributed to the process of lung fibrosis." (PMID 36750914, 2023). "MIF has been shown to have anti-fibrotic effects.The overexpression of protein S in lung cells reduces bleomycin-induced pulmonary fibrosis through the interaction between PROS1-AXL and communication with smooth muscle cells." (PMID 37409114, 2023). "It is of interest that small molecule MIF inhibitors have been found to prevent fibrosis in an in vivo model of bleomycin-induced pulmonary fibrosis, thus dismantling the fibrogenetic role of MIF." (PMID 31752120, 2019). "This present translational study confirms a potential role for MIF in a murine model of BLM-induced pulmonary fibrosis." (PMID 30567353, 2018). "In patients with idiopathic pulmonary fibrosis, MIF levels were observed to be significantly higher than the controls." (PMID 27313397, 2016). "This suggests that MIF is a pleiotropic cytokine involved in the pathogenesis of idiopathic pulmonary fibrosis." (PMID 27313397, 2016). "In line with this notion, a recent clinical study also demonstrated that MIF is up-regulated in both lung tissue and serum of idiopathic pulmonary fibrosis patients." (PMID 25826375, 2015). "Furthermore, we identified fibrosis-associated signaling pathways, including MIF and GAS signaling pathways, which were found to be upregulated in lung fibrosis." (PMID 39062997, 2024). "The relationship between ITGA10 and MIF is still lacking relevant evidence and the future development of inhibitors targeting MIF may contribute to the treatment of pulmonary fibrosis." (PMID 36936416, 2023). "MIF has been suggested to be a key mediator that promotes fibrosis by activating CD74 in liver, renal and pulmonary fibrosis models." (PMID 41225611, 2025). "Macrophage migration inhibitory factor (MIF) inhibition attenuated lung injury and ECM deposition in rats with BLM-induced pulmonary fibrosis." (PMID 36834561, 2023).